MFSD8 (major facilitator superfamily domain containing 8)
Diseases named in the same sentence as MFSD8 in open-access papers:
MFSD8 is named in the same sentence as 55 diseases in open-access papers, as found by Europe PMC text mining. Sharing a sentence is not in itself a finding about the gene and the disease. The quoted sentences say what the papers report.
neuronal ceroid lipofuscinosis (17 papers, 2015 to 2025). "For a variant in MFSD8 linked to neuronal ceroid lipofuscinosis and non‐syndromic retinopathy, as well as variants in OPA1‐associated with dominant optic atrophy, we found strong concordance between minigene assay results and patient‐derived cDNA analyses." (PMID 40304364, 2025). "MFSD8 variants have been identified in six unrelated patients with isolated retinal dystrophy and in one patient with late-infantile neuronal ceroid lipofuscinosis." (PMID 35457110, 2022). "Biallelic gene defects in MFSD8 are not only a cause of the late-infantile form of neuronal ceroid lipofuscinosis, but also of rare isolated retinal degeneration." (PMID 35457110, 2022). "Biallelic MFSD8 variants are an established cause of severe late‐infantile subtype of neuronal ceroid lipofuscinosis (v‐LINCL), a severe lysosomal storage disorder, but have also been associated with nonsyndromic adult‐onset maculopathy." (PMID 31721179, 2020). "Mutations in MFSD8 are associated with Neuronal Ceroid Lipofuscinosis (NCL), a progressive neurodegenerative disorder characterized by the intracellular accumulation of auto-fluorescent lipo-pigment storage material in the brain." (PMID 28794409, 2017). "In previous studies, the MFSD8 gene mutations were the most common genetic cause of variant late-infantile neuronal ceroid lipofuscinosis (vLINCL), also termed as ceroid lipofuscinosis neuronal 7 disease (CLN7, OMIM 610951), which had an onset age of 1.5 to 5 years." (PMID 34457359, 2021). "In humans, a form of the neuronal ceroid lipofuscinosis (neuronal ceroid lipofuscinosis 7, CLN7) is associated with pathogenic variants in MFSD8, which encodes an MFS transporter that moves small solutes (yet to be identified) across membranes." (PMID 40050712, 2025). "In recent years, there is growing recognition that genes initially associated with severe LSDs, such as neuronal ceroid lipofuscinosis (CLN3 and MFSD8) and mucopolysaccharidosis type IIIC (HGSNAT), can also cause non-syndromic retinal dystrophy." (PMID 38863195, 2024). "While variants in genes associated with neuronal ceroid lipofuscinosis (CLN3 (OMIM 607042), CLN5 (OMIM 608102), and MFSD8/CLN7 (OMIM611124)) typically lead to severe neuronal dysfunction and lysosomal storage in neurons and the peripheral tissues, some variants present with isolated retina disease." (PMID 35226187, 2022). "Neuronal ceroid lipofuscinosis (NCL) is a rare group of lethal neurodegenerative lysosomal storage diseases, in which a homozygous single base-pair deletion (c.846delT) in the canine CLN7/MFSD8 gene has been identified as a causative mutation in Chihuahuas." (PMID 35565635, 2022). "Here we have utilized Drosophila as a model system to identify an in vivo role for Cln7/MFSD8, the protein whose activity is reduced in late-infantile neuronal ceroid lipofuscinosis, an early onset childhood neurodegenerative disease." (PMID 31666534, 2019).
Batten disease (14 papers, 2018 to 2025). "In another example, an SVA element was found to cause exon-trapping in MFSD8 (or CLN7 MIM# 610951) in a child with Batten disease, a defect resolved by a personalized antisense-oligonucleotide drug." (PMID 37506127, 2023). "Mutations in MFSD8 are associated with a subtype of Batten disease called CLN7 disease." (PMID 35756993, 2022). "CLN7 Batten disease, also known as variant late infantile neuronal ceroid lipofuscinosis type 7 (vLINCL7), is an ultra-rare form of Batten disease caused by biallelic mutations in MFSD8 (CLN7), which encodes a putative lysosomal transporter of unknown function." (PMID 35229731, 2022). "Commonly known as Batten disease, the different subtypes are each caused by a mutation in a distinct ceroid lipofuscinosis neuronal (CLN) gene (PPT1/CLN1, TPP1/CLN2, CLN3, DNAJC5/CLN4, CLN5, CLN6, MFSD8/CLN7, CLN8, CTSD/CLN10, PGRN/CLN11, ATP13A2/CLN12, CTSF/CLN13)." (PMID 35252181, 2022). "Indeed, mutations in MFSD8, which encodes a lysosomal protein with 12‐predicted transmembrane domains and unknown function, result in histological and phenotypical similarities to another form of Batten disease, CLN7." (PMID 31568712, 2019).
neuronal ceroid lipofuscinosis type 7 (9 papers, 2018 to 2025). "A homozygous deletion of exon 2 of the MFSD8 gene is associated with neuronal ceroid lipofuscinosis type 7 and a homozygous deletion of 16 exons in PARK7 was detected in a child with pathogenic SACS mutations." (PMID 34791078, 2022). "The variant late infantile neuronal ceroid lipofuscinosis type 7 (vLINCL7 or CLN7) disease is a lysosomal storage disease (LSD) caused by a mutation in the gene named major facilitator superfamily domain containing 8 (MFSD8)." (PMID 35025759, 2022). "Mutations in the MFSD8 gene cause the neuronal ceroid lipofuscinosis 7 disease, characterized by the accumulation of proteins and other substances in lysosomes." (PMID 34348663, 2021). "Lastly, in the lysosomal storage cohort, testing also identified two (4.7%; IDs 23 and 24) patients with pathogenic variants in MFSD8 associated with neuronal ceroid lipofuscinosis type 7 (CLN7 disease)." (PMID 34469436, 2021). "Trio whole exome sequencing, Sanger validation, and segregation analysis discovered a novel in-frame small deletion c.325_339del (p.Val109_Ile113del) in MFSD8 gene associated with neuronal ceroid lipofuscinosis type 7." (PMID 30249282, 2018). "For instance, recent proteomics analysis has revealed that one of the proteins which is markedly downregulated in neuronal ceroid lipofuscinosis type 7, is, besides MFSD8 itself, CLN5." (PMID 30548430, 2019). "Neuronal ceroid lipofuscinosis type 7 (CLN7) disease is a lysosomal storage disease caused by mutations in the facilitator superfamily domain containing 8 (MFSD8) gene, which encodes a membrane-bound lysosomal protein, MFSD8." (PMID 35025759, 2022). "A phenotype-oriented evaluation of the gene content of both regions led to the selection of the MFSD8 gene (OMIM: * 611124, responsible for neuronal ceroid lipofuscinosis, type 7) for further analyses." (PMID 36833170, 2023).
lysosomal storage disease (8 papers, 2019 to 2025). A metabolic disorder caused by mutations in proteins critical for lysosomal function, including lysosomal enzymes, lysosomal integral membrane proteins, and proteins involved in the post-translational modification and trafficking of lysosomal proteins. "Neuronal Ceroid Lipofuscinoses type 7 (CLN7) is a paediatric lysosomal storage disease caused by mutations of the MFSD8 gene." (PMID 41314141, 2025). "In essence, NCLs encompass a group of inherited lysosomal storage disorders, with NCL type 7 representing a rare subtype caused by mutations in the MFSD8 gene." (PMID 39555201, 2024). "Finally, mfsd-8 (human orthologue CLN-7) is a lysosomal chloride channel important for lysosomal function, and mutations of CLN-7 lead to a lysosomal storage disorder." (PMID 40655094, 2025). "This lysosomal storage disease results from mutations of the MFSD8 gene and there are no available therapies." (PMID 41314141, 2025).
CLN7 disease (6 papers, 2019 to 2025). "Mutations in major facilitator superfamily domain-containing 8 (MFSD8) cause a late-infantile form of NCL called CLN7 disease." (PMID 35756993, 2022). "Mutations in CLN7/MFS domain-containing 8 (CLN7/MFSD8) are responsible for late-infantile onset NCL (LINCL or CLN7 disease), with disease onset at 1.5–5 years of age4." (PMID 31666534, 2019).
retinal degeneration (5 papers, 2012 to 2023). Degeneration of the retina. "Retinal degeneration in MFSD8-linked LINCL presents as EOSRD, and is clearly distinguishable from isolated phenotypes." (PMID 35457110, 2022). "We report clinical and genetic data of seven patients compound heterozygous or homozygous for variants in MFSD8, issued from a French cohort with inherited retinal degeneration, and two additional patients retrieved from a Swiss cohort." (PMID 35457110, 2022). "Besides late infantile NCL, biallelic variants in MFSD8 can be responsible for non-syndromic retinal degeneration (NSRD) of a variable degree, ranging from a milder macular disease to a widespread rod-cone dystrophy with severe macular involvement." (PMID 36833170, 2023). "Our results confirm that MFSD8 is a rare cause of retinal degeneration as patients carrying biallelic variants in this gene represent only 5/1049 (0.47%) of the total number of cases sequenced by large NGS panels and 5/340 (1.5%) of the patients with macular dystrophy or cone/cone–rod dystrophy." (PMID 35457110, 2022).
Macular dystrophy (4 papers, 2020 to 2025). Macular dystrophy is a nonspecific term for retinal degeneration, generally confined to the macula, usually presumed of genetic origin. "This study identified novel compound heterozygous variants, c.1066C>T and c.1102+2T>C, in the MFSD8 gene as being possibly responsible for the family's macular dystrophy phenotype." (PMID 34457359, 2021). "The novel compound heterozygous variants, c.1066C>T (p.Pro356Ser) and c.1102+2T>C, in the MFSD8 gene are likely responsible for the isolated macular dystrophy phenotype in this family." (PMID 34457359, 2021). "Novel compound heterozygous variants, c.1066C>T (p.Pro356Ser) and c.1102+2T>C, in the major facilitator superfamily domain containing 8 gene (MFSD8) were suspected to be involved in this family's macular dystrophy phenotype." (PMID 34457359, 2021). "In more than 270 known retinopathies genes (based on RetNet), only two novel variants, c.1066C>T and c.1102+2T>C, in the MFSD8 gene (NG_008657.1 and NM_152778.4) were identified as being responsible for the macular dystrophy phenotype according to filtering steps of the methods." (PMID 34457359, 2021). "Nevertheless, no hallmarks or severe neurologic symptoms were observed in the proband, supporting the MFSD8 gene as a nonsyndromic macular dystrophy gene." (PMID 34457359, 2021).
retinal disease (3 papers, 2018 to 2022). "This study of seven patients carrying MFSD8 variants showed that isolated retinal diseases are associated with combination of one severe and one mild or moderately severe variant, whereas the syndromic form with an EOSRD phenotype seems to be related to severe variants." (PMID 35457110, 2022). "Most interestingly, GRIPT was able to identify novel retinal disease genes, i.e., POMGNT1 (p = 2.81 × 10−10) and MFSD8 (p = 2.81 × 10−10)." (PMID 30477545, 2018).
amyotrophic lateral sclerosis (2 papers, 2025). Amyotrophic lateral sclerosis (ALS) is a neurodegenerative disease characterized by progressive muscular paralysis reflecting degeneration of motor neurons in the primary motor cortex, corticospinal tracts, brainstem and spinal cord. "CTSF and MFSD8 (CLN7) are involved in the lysosomal–autosomal pathway that contributes to amyotrophic lateral sclerosis (ALS)/FTD." (PMID 39925015, 2025).
Ataxia (2 papers, 2018 to 2021). Ataxia refers to impaired coordination of voluntary muscle movement. "The loss-of-function variants in the MFSD8 gene are mainly observed in NCL 7 (CLN7), which presents with deterioration of cognitive and motor skills in combination with seizures, ataxia, and progressive loss of vision." (PMID 34567070, 2021).
Brain atrophy (2 papers, 2015 to 2018). Partial or complete wasting (loss) of brain tissue that was once present. "However, unlike the human CLN7 patients and our dog, the Mfsd8 nullizygous mice did not exhibit any neurologic signs, behavior changes, brain atrophy or premature death." (PMID 25551667, 2015).
Cerebellar atrophy (2 papers, 2016 to 2023). Cerebellar atrophy is defined as a cerebellum with initially normal structures, in a posterior fossa with normal size, which displays enlarged fissures (interfolial spaces) in comparison to the foliae secondary to loss of tissue. "The cerebral and cerebellar atrophy detected in the meantime by MRI, along with the suspicion of accumulation of ceroid lipopigment in neurons, prompted us to perform targeted MFSD8 sequencing." (PMID 36833170, 2023). "Based on the preliminary diagnosis of cerebral and cerebellar atrophy on brain MRI, only three genes causative of AR forms of white matter diseases were lying within the observed 24 Mb regions of homozygosity, including EXOSC9 (OMIM *606180), SPATA5 (OMIM *613940) and MFSD8 (OMIM *611124)." (PMID 36833170, 2023).
cone-rod dystrophy (2 papers, 2021 to 2023). Inherited retinal dystrophies that belong to the group of pigmentary retinopathies. "Hypomorphic MFSD8 variants have been reported as causative of a nonsyndromic form with only macular disease, or widespread rod-cone dystrophy with severe macular involvement." (PMID 36833170, 2023). "The findings were further underpinned by several recent reports of compound heterozygous or homozygous MFSD8 gene variants identified in patients with nonsyndromic macular dystrophy, nonsyndromic retinitis pigmentosa, or more severe rod-cone dystrophy." (PMID 34457359, 2021).
frontotemporal dementia (2 papers, 2023 to 2025). Frontotemporal dementia (FTD) comprises a group of neurodegenerative disorders, characterized by progressive changes in behavior, executive dysfunction and language impairment, as a result of degeneration of the medial prefrontal and frontoinsular cortices. "Moreover, recently, through case-control NGS association studies, Geier and colleagues suggested that rare variants in MFSD8 may act as genetic risk factors for frontotemporal dementia (FTLD)." (PMID 36833170, 2023).
isolated macular dystrophy (2 papers, 2021 to 2025). "Similarly, a proximal c.1102G>C variant in the MFSD8 gene was shown to result in a skipping of exon 11 and caused isolated macular dystrophy when paired with a c.1006G>C (p.Glu336Gln) variant." (PMID 34457359, 2021).
macular dystrophy with central cone involvement (2 papers, 2020 to 2021). "Recently, one study showed that the MFSD8 mutation can also cause nonsyndromic macular dystrophy with central cone involvement (CCMD)." (PMID 34567070, 2021). "Genetic variants of MFSD8 also were reported in human patients with ocular disease (nonsyndromic macular dystrophy with central cone involvement [CCMD]) without neurological features, suggesting that NCL and CCMD are likely not different disease entities but rather allelic diseases." (PMID 31860737, 2020).
autism (1 paper, 2020). Persistent deficits in social interaction and communication and interaction as well as a markedly restricted repertoire of activity and interest as well as repetitive patterns of behavior. "On the other hand, variants in MFSD8 have been reported to cause autism and developmental regression, but only in an autosomal recessive condition." (PMID 32722525, 2020).
Cognitive impairment (1 paper, 2024). Abnormal cognition is characterized by deficits in thinking, reasoning, or remembering. "Two years later, she developed seizures and cognitive impairment, leading to a diagnosis of NCL7 resulting from a homozygote mutation in the MFSD8 gene." (PMID 39555201, 2024).
microcephaly (1 paper, 2023). A congenital or acquired developmental disorder in which the circumference of the head is smaller than normal for the person's age and sex. "We detected a novel homozygous non-canonical splice-site variant in MFSD8 in a 5-year-old girl who presented with progressive neurocognitive impairment and microcephaly." (PMID 36833170, 2023).
Retinal dystrophy (1 paper, 2022). Retinal dystrophy is an abnormality of the retina associated with a hereditary process. "All MFSD8 variants associated with isolated retinal dystrophy (MD, COD/CORD) are located in the transmembrane alpha helices, except p.(Glu381*), located at the most extracellular side of loop 9, nearby the two proteolytic cleavage sites Asn370 and Asn376." (PMID 35457110, 2022). "In this study, we report ocular phenotype of patients with MFSD8-related isolated retinal dystrophy and LINCL, describe novel MFSD8 variants and their functional repercussion, and present a tentative of genotype–phenotype correlation." (PMID 35457110, 2022). "All isolated retinal dystrophy cases of our series and from literature harboured one severe and one mild or moderately severe MFSD8 variant, whereas all LINCL cases carried two severe MFSD8 variants." (PMID 35457110, 2022). "Isolated retinal dystrophy associated with MFSD8 gene defects manifests as MD, COD or CORD, and could mimic STGD1." (PMID 35457110, 2022).
Stargardt disease (1 paper, 2020). "Using WES, we identified two novel MFSD8 variants c.590del p.(Gly197Valfs*2) and c.439+3A>C p.(Ile67Glufs*3) in a now 12‐year‐old proband with isolated maculopathy, initially diagnosed as atypical Stargardt disease." (PMID 31721179, 2020).
Visual impairment (1 paper, 2021). "Some patients with vLINCL displayed visual impairment early, indicating that the retina is more sensitive to the MFSD8 gene variant than the brain, and retinal neuron loss may precede brain neuron loss, supported by the findings in the Mfsd8-deficient mice." (PMID 34457359, 2021).
Wolf-Hirschhorn syndrome (1 paper, 2022). Wolf-Hirschhorn syndrome (WHS) is a developmental disorder characterized by typical craniofacial features, prenatal and postnatal growth impairment, intellectual disability, severe delayed psychomotor development, seizures, and hypotonia. "MFSD8 and MFSD10 have been linked to the Wolf-Hirschhorn syndrome and to LINCL (late-infantile-onset neuronal ceroid lipofuscinoses), respectively, and MFSD8 seems to be localized in the lysosomes." (PMID 35901096, 2022).
ZIKV infection (1 paper, 2020). "For example, the alternative splicing of SLC35B6, MFSD8, and CHID1 might affect ZIKV infection." (PMID 32380717, 2020).
retinopathy (6 papers, 2020 to 2025). "Variants in MFSD8 can cause neuronal ceroid lipofuscinoses (NCLs) as well as nonsyndromic retinopathy." (PMID 35216386, 2022). "In case of residual functional CLN7 protein however, slower disease progression or even an atypical disease course is seen, with the macula being first affected and eventually leading to a more widespread retinopathy or even neuronal loss in line with the severity of the MFSD8 pathogenic variants." (PMID 31721179, 2020). "For the MFSD8 gene, the same genotype has been shown to cause both NCL and nonsyndromic retinopathy, but only in unrelated patients." (PMID 35216386, 2022). "Patients with biallelic variants in MFSD8 usually present classical NCL symptoms such as seizures, visual loss, mental regression, and ataxia, but cases with isolated retinopathy have been reported as well." (PMID 35216386, 2022). "Retinopathy caused by MFSD8 mutations is either not further specified or suggestive for RP." (PMID 34567070, 2021).
MFSD8 also shares sentences with these, for which no sentence is quoted: late infantile NCL (5 papers); Bardet-Biedl syndrome (2); cancer (2); neurodegenerative disease (2); retinitis pigmentosa (2); Atrophy (1); cone dystrophy (1); cortical dysplasia (1); dominant optic atrophy (1); epilepsy (1); genetic disorder (1); giant axonal neuropathy (1); GM1 gangliosidosis (1); infection (1); Kaya-Barakat-Masson syndrome (1); macular degeneration (1); mitochondrial disease (1); mucopolysaccharidosis type IIIC (1); myeloid leukemia (1); myoclonus epilepsy (1); neuroblastoma (1); Onset (1); osteopetrosis (1); Rett syndrome (1); sphingolipidoses (1); spinal muscular atrophy (1); transthyretin amyloidosis (1); tumor (1); variant late-infantile neuronal ceroid lipofuscinosis (1); Wolman disease (1).